TF (transferrin)
Diseases named in the same sentence as TF in open-access papers (continued):
Sharing a sentence is not in itself a finding about the gene and the disease.
diabetes (104 papers, 2005 to 2025). "Higher transferrin saturation is associated with higher mortality rates and faster progression of diabetes and its complications, making it a relevant marker for further investigation." (PMID 40895225, 2024). "Uncontrolled diabetes or steroid use can cause hyperglycemia, which results in the glycosylation of iron-binding proteins such as transferrin and ferritin." (PMID 37123703, 2023). "The other admission variables associated with the risk of death found in the presentstudy were age, diabetes, initiation of HD in a hospital, body mass index,transferrin saturation index, hemoglobin, albumin and alkaline phosphatase levelsand fluid overload." (PMID 36662571, 2023). "A total of 24 osteoporosis-related genes, including IGF1, IL6, pyruvate dehydrogenase kinase 4 (PDK4), PPARGC1A, and TF, were also associated with obesity and diabetes." (PMID 35328013, 2022). "Several studies have linked transferrin with other chronic conditions strongly associated with CVD such as diabetes and chronic kidney disease." (PMID 35538408, 2022). "In comparison with our study, previous data on PTB coinfection with diabetes mellitus or HIV disease is associated with reduced transferrin levels." (PMID 36341407, 2022). "High transferrin levels have also been associated with diabetes and metabolic syndrome, which are known risk factors for severe COVID-19 disease." (PMID 32751741, 2020). "Urine IgG and transferrin excretion has been previously observed in normoalbuminuric patients with diabetes and has been associated with hypertension and hyperfiltration." (PMID 30158836, 2018). "When the plasma Fe content exceeds the iron-binding capacity of transferrin, Fe accumulates in the body and causes cell damage with different clinical symptoms, such as inflammation, arrhythmias and diabetes mellitus." (PMID 29164513, 2018). "As demonstrated in three independent studies, transferrin saturation can act as an independent risk marker for any form of diabetes mellitus, and a value ≥50% alleviates the risk of developing T2DM by two to three times." (PMID 29083385, 2016). "In our previous study, we showed that low transferrin saturation was robustly associated with pre-diabetes." (PMID 25204761, 2014). "Similarly, abnormal activities of a-antitrypsin, transferrin and hemopexin are all implicated in diabetes." (PMID 35768493, 2022). "Low transferrin saturation is associated with a higher risk of pre-diabetes." (PMID 34184611, 2021). "However, when cardiovascular risk factors (smoking, hypertension, diabetes, and dyslipidemia) were analyzed, the proportion of TF-EVs was significantly increased only in PV patients with hypertension (p < 0.05) and positively correlated with age (p < 0.05)." (PMID 34638452, 2021). "In support of APP glycosylation as a risk factor for disease, synthesis and glycosylation of AGP, haptoglobin, and transferrin are associated with a number of chronic diseases such as pancreatitis, rheumatoid arthritis, diabetes, and inflammatory lung conditions." (PMID 28642810, 2017). "In contrast, higher body mass index, Kt/Vurea, hemoglobin, albumin, and transferrin saturation rate, along with statin use and the presence of CVA or diabetes, tended to be associated with lower ERI quartiles." (PMID 40283642, 2025). "Quantifications of metal-sequestering proteins lactoferrin, transferrin, calprotectin, and psoriasin from intact skin and infected wounds indicated that nutritional immunity, especially iron restriction, is delayed in diabetes." (PMID 41427730, 2025). "Typically, systemic findings precede neurologic findings by approximately ten years and include mild microcytic anemia, low serum iron, high serum ferritin, low transferrin saturation, diabetes mellitus, and degenerative changes in the retina." (PMID 40729217, 2024).
diabetes (continued). "Those with advanced fibrosis were significantly older and had significantly higher alcohol consumption, proportions of individuals with arthritis or diabetes mellitus, serum transferrin saturation and ferritin levels, HIC, HII, and mobilizable iron stores." (PMID 39131712, 2024). "As compared to premenopausal women, postmenopausal women had higher ferritin, BMI, CRP, and SBP levels, more prevalent CVD and diabetes, reported higher consumption of anti-diabetic and antihypertensive medications, and had lower transferrin levels." (PMID 38715055, 2024). "Compared with the non-iron-based only group, patients in the iron-based group were younger, had more diabetes, higher transferrin saturation, and higher ferritin, and received fewer intravenous or oral iron drugs." (PMID 37749304, 2023). "Hyperglycemia due to uncontrolled diabetes or steroid use can lead to glycosylation of iron-binding proteins, such as transferrin and ferritin, thereby reducing their iron-binding capacity and releasing free iron to Mucorales." (PMID 37123703, 2023). "Our study was aimed at evaluating albumin, globulin, and transferrin imbalance in children who have been recently diagnosed with CD and CD in comorbidity with type 1 diabetes mellitus." (PMID 36778054, 2023). "In participants suffering from both diabetes and celiac (group D), the transferrin was observed to be 406.4 mg/dl." (PMID 36778054, 2023). "Participants with diabetes had a higher serum iron (frozen) level and transferrin saturation level and a lower serum UIBC." (PMID 37344885, 2023). "Plasma iron, ferritin, and transferrin were higher in the diabetes group compared with non-diabetes." (PMID 38455289, 2022). "What is clear from the discussion above is that TMAO and transferrin each demonstrate associations with various chronic diseases such as CKD, diabetes, and CVD." (PMID 35538408, 2022). "In the case of patients with diabetes mellitus, the concentration of antioxidants such as vitamin A and E, albumin and transferrin, among others, decreases." (PMID 36145129, 2022). "The potential relationship and causal pathways of transferrin, free iron, Clostridia gut microbiota, serum TMAO, diabetes, chronic kidney disease, and CVD risk are shown as a visual diagram." (PMID 35538408, 2022). "In chemically-induced diabetes models, γ-TF and a γ-TT-rich fraction (α-TF: 21.8%; γ-TF: 1.0%; α-TT: 23.4%; and γ-TT: 37.4%) dose-dependently reduced inflammation-related markers including NF-κB, MCP-1, IL-6, IL-1β, and TNF-α in skeletal muscle and plasma." (PMID 33919211, 2021). "The independent effect of serum TF-UP level on the probability of acute ischemic stroke was estimated by multivariate logistic regression, with adjustment for age, diabetes mellitus, hypertension, and previous ischemic heart diseases." (PMID 33633672, 2021). "The serotransferrin protein (TF) level was increased in subjects with diabetes compared with that in the NG and GI groups (45% and 38%, respectively)." (PMID 33587339, 2021). "Numbers of patients with chronic liver disease, CVA, diabetes mellitus, as well as serum levels of albumin, K, Ca, and parathyroid hormone, transferrin saturation, hemoglobin and platelets were similar between the groups." (PMID 31999778, 2020). "Thus, further studies are warranted to determine whether SF, transferrin, and Hb reduction may improve the HU risk factors, and thereby reduce the risk of developing gout, diabetes mellitus, cardiovascular diseases, nonalcoholic fatty liver disease, and cancer." (PMID 29425155, 2018). "Chronic or inflammatory diseases, such as diabetes, result in low transferrin and iron, which is a sign that the liver cells are damaged and the transport of these ions through beta globulin cells in the blood stream is impaired." (PMID 24971142, 2014). "Previous history of cardiopathy, peripheral vascular disease, diabetes, serum albumin and transferrin were independent predictors of future CV events." (PMID 24959538, 2013).
diabetes (continued). "The risk factors for the use of antihypertensive agents were the presence of vascular amputation, a history of smoking, the presence of a diagnosis of type 2 diabetes mellitus, a % transferrin saturation > 26.75%, male sex, and hemodialysis as the treatment type." (PMID 39825259, 2025). "However, the Q4 had a lower proportion of diabetes and transferrin saturation, hemoglobin, albumin, calcium, phosphorus, and creatinine levels than the other groups." (PMID 40283642, 2025). "Older age, male gender, risky occupations, fever, headache, muscle ache, dyspnea, diarrhea, diabetes mellitus, heart disease, bronchial asthma, lower platelets, low absolute lymphocytic count, higher NLR, PLR, CRP, transferrin, LDH, and D dimer were associated with more-severe COVID-19." (PMID 39452786, 2024). "In the present investigation, NGS data analysis revealed that the mechanism of occurrence of diabetes mellitus and obesity might be related to the expression of miRNA and TF." (PMID 36837510, 2023). "Furthermore, we constructed a target gene–miRNA regulatory network and target gene–TF regulatory network based on these key genes to investigate the potential relationships between genes and subject with diabetes and obesity." (PMID 36837510, 2023). "In diabetes mellitus, it has been hypothesized that glycochelates, (glycates protein and peptides) might detach iron from transferrin and chelate it with a greater affinity." (PMID 36830061, 2023). "Moreover, a 4-protein (SERPINA5, VPS4A, CP, TF) classifier was built to predict early stage DKD3 from diabetes." (PMID 34963468, 2021). "Interestingly, this phenomenon has also been observed in pre-diabetes, concomitant with low transferrin saturation levels." (PMID 34065122, 2021). "After performing the dimension reduction from the 24 overlapping DEPs from discovery and validation datasets, a 4-protein classifier (SERPINA5, VPS4A, CP, TF) could distinguish diabetes from DKD3." (PMID 34963468, 2021). "However, the effect of TF-UP/Alb-UP was dramatically confounded by diabetes mellitus, with an OR of 10.93, much >1.21 for TF-UP." (PMID 33633672, 2021). "However, there is a controversy on the status of transferrin in human diabetes, in which decreased, normal and increased levels have been reported." (PMID 33271797, 2020). "Moreover, urine albumin, uACR, urine NGAL and NGAL/creatinine ratio, urine transferrin, urine IgG, urine uromodulin, and uromodulin/creatinine ratio significantly correlated with diabetes control as reflected by HbA1c concentrations." (PMID 30158836, 2018). "In diabetes, decreased plasma transferrin concentrations could lead to an increase in lipid peroxidation by enhancing the pro-oxidant effects of iron." (PMID 30395577, 2018). "Besides this, despite not being assessed in the present study, it has been demonstrated that changes in normal ranges of ferritin and transferrin saturation can influence diabetes and cardiovascular risks." (PMID 29518910, 2018). "Albuminuria, urine NGAL, transferrin, IgG, and uromodulin correlated with diabetes control." (PMID 30158836, 2018). "It should be noted that the concentrations of acute-phase proteins—including ceruloplasmin (CP), transferrin, and albumin—may not reliably indicate iron metabolism in the context of diabetes-associated chronic inflammation and oxidative stress." (PMID 40871742, 2025). "In HH, biochemical abnormalities, such as elevated transferrin saturation and ferritin levels, typically precede clinical symptoms, which can range from mild fatigue and arthralgia to severe conditions like hepatocellular carcinoma, diabetes mellitus, and cardiac abnormalities." (PMID 39720661, 2024). "Diabetes and related ketoacidosis-like conditions lower the blood's pH, and high serum glucose, iron, acidic conditions, and β-hydroxyl butyrate, which impair the chelation of iron from transferrin, are all add-on factors that favor the growth of and invasion by fungus." (PMID 38618586, 2024).
diabetes (continued). "In addition, The Cohort on Diabetes and Atherosclerosis Maastricht study observed associations between iron metabolism (ferritin, transferrin, serum iron, and non-transferrin-bound iron) with adipocyte IR and T2DM." (PMID 34836405, 2021). "Importantly, transferrin has been utilized as a trans-mucosal delivery modality for oral insulin preparations in a rat model of diabetes, suggesting that the CD71-transferrin transcytotic route has a realistic potential as an effective mucosal vaccine delivery strategy." (PMID 22119743, 2012). "Moreover, one recent study showed that compared with diabetes patients with lower BMI (<30 kg/m2), the transferrin saturation of subjects with higher BMI (>30 kg/m2) was significantly lower, which may suggest the possibility of lower serum iron levels among T2D patients with obesity." (PMID 36904197, 2023). "The results were consistent with previous studies, indicating that the synthesis of TF and FVII is more prominent in diabetes." (PMID 33553435, 2021). "Meanwhile, there were significantly decreased concentrations of L-Serine and SM(d18:1/22:1(13Z)) in the TF group compared with the M group and indicated that the degradation of the concentration of sphingolipid metabolites might have a positive role in anti-diabetes." (PMID 34970582, 2021). "Consequently, we identified a novel TF-miRNA GRN specific to Lin-/VEGF-R2+ D-EPCs (D-EPC-GRN), putative genomic drivers (TFs and miRNAs) and significant FFL network modules that involve dysregulated TFs/genes, associated miRNAs as well as diabetes-associated genes." (PMID 29995913, 2018). "Increased serum ferritin could be due to hemochromatosis causing both hepatic abnormalities and diabetes; however, hemochromatosis can be ruled out here because other iron parameters, such as transferrin and transferrin saturation, which are typically increased in iron storage diseases, were normal." (PMID 30132197, 2018). "Additionally, non-transferrin-bound iron (NTBI) is commonly present in type 2 diabetic patients, with a higher prevalence in advanced diabetes patients." (PMID 40871742, 2025). "The most common non-neurological symptoms or signs were diabetes mellitus, skin pigmentation, increased ferritin and transferrin saturation, and less commonly hepatomegaly." (PMID 40941762, 2025). "Transferrin saturation, estimated by serum iron (frozen) and serum UIBC, was also associated with the risk of diabetes; the P-value for non-linear < 0.001." (PMID 37344885, 2023). "In our study, in a small group of subjects affected by PAD, with and without diabetes mellitus, with normal values of serum iron, ferritin, and transferrin, we have shown that the pool of NTBI is mostly bound to HSA." (PMID 36830061, 2023). "There were no between‐group differences in the prevalence of diabetes, body mass index, serum transferrin, ferritin, and glucose levels." (PMID 35128728, 2022). "Still, in case of urine IgG, transferrin, NGAL, and KIM-1, the difference between A1 and A2 subgroups remained significant after adjustment for age, diabetes duration, and comorbidities (hypertension and heart failure) as well as treatment with renin-angiotensin-aldosterone system inhibitors." (PMID 30158836, 2018). "The highest concentration of transferrin in urine observed among the CBS population could potentially reflect its multicausal character and the presence of nephrotoxic comorbidities (e.g., diabetes), as it is a marker of subclinical tubular alterations." (PMID 41225971, 2025). "Furthermore, although not differentially O-GlcNAc-modified in diabetes compared to the BMI-matched controls, the TfR was identified in all placental O-GlcNAcomes, with 5 modified residues, and its ligand, transferrin, was more O-GlcNAcyalted (19.5-fold) in placentas from women with T2D." (PMID 34667181, 2021).
hemochromatosis (96 papers, 2005 to 2025). A disorder of iron metabolism characterized by a triad of HEMOSIDEROSIS; LIVER CIRRHOSIS; and DIABETES MELLITUS. "Elevated serum ferritin (>2000 ng/mL) and transferrin saturation (>85%) that were present in our case are the hallmark biochemical findings of hemochromatosis." (PMID 40979821, 2025). "In humans, the gene encoding transferrin is located on chromosome 3q21, encoding a molecule that binds to hemochromatosis (HFE) protein to form a stable complex that regulates iron transport." (PMID 36362642, 2022). "The hemochromatosis HFE gene polymorphism (H63D at rs1799945) is also associated with reduced transferrin levels and white matter fiber integrity in the external capsule." (PMID 36362642, 2022). "It is pertinent to note that dysregulated hepcidin is a defining feature of hemochromatosis, a condition characterized by hepcidin deficiency, increased plasma iron levels and transferrin saturation." (PMID 33066821, 2020). "In fact, the epistatic interaction between P589S ‘rs1049296’ in the transferrin gene (TF) and C282Y ‘rs1800562’ in the hemochromatosis gene (‘HFE’) result in the increased risk of cognitive impairment and Alzheimer’s and Parkinson’s diseases." (PMID 30190574, 2018). "Further laboratory data such as ferritin, transferrin saturation, and search for hemochromatosis gene mutations are needed to confirm this diagnosis." (PMID 27363994, 2016). "Surprisingly, if the diagnosis is based on traditional laboratory markers (i.e., serum ferritin and transferrin saturation) the incidence of the disease is higher as compared to that resulting from the analysis of hemochromatosis gene (HFE) mutations." (PMID 24222913, 2013). "We evaluated associations of manganese with functional variants in three candidate iron metabolism genes: HFE [hemochromatosis], TF [transferrin], and ALAD [δ-aminolevulinic acid dehydratase]." (PMID 22074419, 2011). "Although an animal study unambiguously showed an effect of H63D mutation on hemochromatosis development, a human twin study established the influence of H63D on transferrin saturation levels." (PMID 16503999, 2006). "Elevations in transferrin saturation and serum iron in OCP users have previously been suggested to be due to hepatic effects of exogenous estrogens, with OCP users more likely to have transferrin saturation levels >45% and be considered at risk of hemochromatosis." (PMID 37487629, 2023). "A polygenic score for TF saturation showed similar patterns of association with outcomes to the iron polygenic score, especially with increasing likelihood of hemochromatosis diagnosis in p.H63D homozygotes (OR per SD of polygenic score, 2.15: 95% CI 1.49–3.09)." (PMID 35567766, 2022). "In addition, hepatocellular carcinoma risk is substantially increased among individuals with hemochromatosis gene mutations and in hemochromatosis patients diagnosed by elevated serum transferrin saturation and ferritin levels." (PMID 32092884, 2020). "The objective of this study was to determine whether maternal and/or infant transferrin (TF) and hemochromatosis (HFE) gene missense variants modify the association between maternal blood lead (MBL) and umbilical cord blood lead (UCBL)." (PMID 25287020, 2014). "However, neither intronic nor exonic keratin variants associated with iron accumulation in hemochromatosis patients as suggested by similar levels for serum iron, transferrin, transferrin saturation, ferritin and HIC and HII indices." (PMID 22412904, 2012). "In HFE-associated hemochromatosis patients, increased transferrin saturation typically precedes elevated ferritin levels and may therefore provide a more accurate representation of iron stores in these individuals than ferritin." (PMID 22074419, 2011). "Our patient had findings supportive of hemochromatosis, including liver function tests three times the upper limit of normal, a ferritin level above 43,000, transferrin saturation of 89%, subclinical hypothyroidism, and hyponatremia." (PMID 40747175, 2025).